MIR602 (microRNA 602)
Synonyms: hsa-mir-602; MIRN602
Gene: MicroRNA gene on chromosome 9 (137,838,419 to 137,838,516, forward strand). Ensembl gene ENSG00000207693.
Diseases named in the same sentence as MIR602 in open-access papers:
MIR602 is named in the same sentence as 5 diseases in open-access papers, as found by Europe PMC text mining. Sharing a sentence is not in itself a finding about the gene and the disease. The quoted sentences say what the papers report.
glioblastoma multiforme (1 paper, 2023). "MIR602 overexpression has been associated with a poor prognosis in oesophageal squamous cell carcinoma and in glioblastoma multiforme and a favourable outcome in pancreatic ductal adenocarcinoma." (PMID 37239316, 2023).
hepatocellular carcinoma (1 paper, 2023). A malignant tumor that arises from hepatocytes. "MIR602 is also involved in Hedgehog signalling in chondrocytes and has anti-apoptotic activities in hepatocellular carcinoma." (PMID 37239316, 2023).
cancer (1 paper, 2023). A tumor composed of atypical neoplastic, often pleomorphic cells that invade other tissues. "Some are known to be tumor suppressor genes (OPCML-IT2), to be related to resistance to cancer therapies (RAC1P3), or to be involved in several cancer processes such as genome stability (XRCC6P2), tumor growth and metastasis (MIR602) and regulation of gene transcription (NME2P2)." (PMID 36647008, 2023).
MIR602 also shares sentences with these, for which no sentence is quoted: pancreatic ductal adenocarcinoma (1 paper); tumor (1).